HGF (hepatocyte growth factor)
Diseases named in the same sentence as HGF in open-access papers (continued):
Sharing a sentence is not in itself a finding about the gene and the disease.
cancer (continued). "The major mechanism of cell adhesion-dependent regulation of cancer cell responses to HGF is achieved through the phosphorylation of cell adhesion molecules and their interacting molecules." (PMID 28475121, 2017). "PSCs interact with cancer cells and influence the progression of the disease through a complex network of signaling molecules including hepatocyte growth factor (HGF)." (PMID 29069737, 2017). "Taken together, these results suggest that HGF downregulates cell proliferation-related genes by upregulating miR-7, which acts to suppress the cancer progression of normal breast cells." (PMID 29133945, 2017). "Aberrant activation of c-Met, a receptor tyrosine kinase, is frequently observed in various cancer types via a hepatocyte growth factor (HGF)-dependent or -independent manner." (PMID 28902178, 2017). "MACC1 was previously reported to mediate invasion and metastasis by regulating HGF/c-Met signaling pathway in several cancer types." (PMID 28624808, 2017). "Understanding factors that contribute to the paracrine HGF/c-Met signaling during cancer-fibroblast interactions will therefore have a positive clinical impact for c-Met overexpressing cancers." (PMID 29296173, 2017). "Our comprehensive results show that IRCR201 is capable of inhibiting a variety of cancer types with HGF-dependent c-Met activation or gene amplification-driven constitutive c-Met activation." (PMID 28902178, 2017). "Cancer cells exposed to hPSC secretions exhibited increased activation/phosphorylation of c-MET most likely in response to HGF in the secretions." (PMID 29100344, 2017). "HGF is an example of a molecule involved in this kind of interaction, wherein cancer cells stimulate fibroblasts to produce HGF that in turn transduces signals through its specific receptor tyrosine kinase MET." (PMID 29202869, 2017). "IRCR201 also demonstrates low agonistic activity and disrupts c-Met signaling pathway activation induced by both HGF-dependent and independent mechanisms in various cancer types, eliciting distinct molecular traits compared to other c-Met-targeting antibodies." (PMID 28902178, 2017). "It has been observed that CAFs actively communicate with cancer cells through growth factors or inflammatory cytokines such as HGF, IL-6, TGF-β, VEGF, FGF, and CXCL12 that can promote tumorigenesis and progression." (PMID 28186964, 2017). "PAK6, one of the least well characterized family members, is required for hepatocyte growth factor (HGF) activated carcinoma cell-cell disassociation." (PMID 27845911, 2017). "Cloudberry extract significantly inhibited particularly HGF-induced cancer cell migration in both cell lines." (PMID 27270323, 2016). "The top five represented canonical pathways associated with extravasation signaling, and cancer-associated HER2 signaling, HGF signaling, and MAPK-signaling." (PMID 26807845, 2016). "Until now, there had many studies to investigate the prognostic value of HGF expression in cancer cells for multiple cancer types." (PMID 27374174, 2016). "Cell viability, cell death and the effects of exosomes on the HGF/c-Met/Akt signaling pathway in cancer cells were analyzed by MTT assays, FACS analysis and Western blotting, respectively." (PMID 27716356, 2016). "Hepatocyte growth factor (HGF) and its receptor c-MET are implicated in cancer cell growth, invasion and metastasis, and angiogenesis." (PMID 27581465, 2016). "Multiple signals are responsible for induction of EMT in cancer cells; in particular, hepatocyte growth factor (HGF), epidermal growth factor (EGF), and transforming growth factor-β (TGF-β)." (PMID 26925388, 2016). "HGF is a protein produced by CAFs that involves in promoting growth, motility and morphogenesis in cancer." (PMID 27374174, 2016). "Previously, a Ran binding protein, RanBPM, was shown to promote HGF-Met signaling, and we have shown that, in a rat cell line, Ran activates Met to promote cancer progression." (PMID 27716616, 2016).
cancer (continued). "Because of its pleiotropic role in oncogenesis and cancer progression, HGF/c-MET is considered to be an important target in anticancer therapy." (PMID 27923392, 2016). "For example, mouse fibroblasts overexpressing HGF were able to initiate cancer in implanted normal human breast epithelia." (PMID 27058757, 2016). "Numerous preclinical and clinical studies have demonstrated that antibody or small-molecule inhibitors targeting MET or HGF are effective anti-cancer therapies." (PMID 27013592, 2016). "We have previously reported that Ephedra Herb suppresses HGF-induced cancer cell motility by prevention of c-Met phosphorylation via inhibition of its tyrosine kinase activity." (PMID 26943796, 2016). "Preclinical studies have provided strong support for the notion that inhibitors of HGF/MET signaling have therapeutic efficacy in a selected group of cancer patients." (PMID 27121052, 2016). "The reduction in Met results in a reduced responsiveness of cancer cells to HGF, including PI3K/Akt activation downstream of Met and cellular properties associated with metastatic potential that are enhanced by HGF stimulation." (PMID 27716616, 2016). "Among the metastatic factors, HGF, a well-known scatter factor, was frequently elevated during the progression of cancers including HCC." (PMID 26840563, 2016). "MT-1 activity is also involved in tumorigenesis of various cancer types and promotes the progression of malignant transformations via cleavage and activation of substrates like hepatocyte growth factor/scatter factor." (PMID 27642598, 2016). "HGF/c-MET has been extensively studied as a therapeutic target in various cancers for the last two decades, especially in lung cancer therapy." (PMID 27923392, 2016). "MET activation promotes the cancer stem cell phenotype and HGF/MET signaling plays a crucial role in the development of resistance to classical cytotoxic therapy and targeted therapy, such as EGFR and BRAF inhibitors." (PMID 27121052, 2016). "Our studies confirmed that the c-Met inhibitory activity of maoto derives from Ephedra Herb, which impairs HGF-induced cancer cell motility by suppressing the HGF-c-Met signaling pathway through inhibition of c-Met tyrosine kinase activity." (PMID 26943796, 2016). "Cancer cells, including cell lines used in this study, commonly overexpress a combination of pro-HGF-activating proteases." (PMID 27121052, 2016). "We confirmed that EFE suppressed hepatocyte growth factor (HGF)-induced cancer cell motility by preventing both HGF-induced phosphorylation of c-Met and its tyrosine kinase activity." (PMID 26943796, 2016). "MMP1 is a matrix metallopeptidase 1 protein involved in proteolysis of ECM and thus in cancer metastasis; HGF is known to induce cell scattering." (PMID 27982133, 2016). "Aberrantly activated MET/HGF signaling correlates with tumorigenesis and metastasis, and is regarded as a robust target for the development of novel anti-cancer treatments." (PMID 27013592, 2016). "Both the MET kinase inhibitor JNJ38877605 and SRI 31215 inhibit signaling between cancer cells and HGF-producing fibroblasts, blocking fibroblast-induced proliferation, EMT and migration of cancer cells." (PMID 27121052, 2016). "HGF/c-Met system functions as a potent pro-angiogenic cue to exacerbate the malignant behavior of cancer cells." (PMID 27191264, 2016). "Aberrant activation of the HGF/c-Met axis is known to promote cytoskeletal changes of many cancer cells, inducing migration, invasion, and eventual metastasis." (PMID 27086914, 2016). "In this review, we discuss the importance of accurate HGF/MET signal detection as a predictive biomarker to guide patient selection for clinical trials of MET-targeted therapies in human cancers." (PMID 27013592, 2016).
cancer (continued). "Activation of the MET receptor tyrosine kinase by its ligand, hepatocyte growth factor (HGF), has been implicated in a variety of cellular processes, including cell proliferation, survival, migration, motility and invasion, all of which may be enhanced in human cancers." (PMID 27013592, 2016). "The HGF-activating proteases are upregulated and the levels of HAI-1/2 are reduced in cancer tissues, resulting in increased activation of HGF and constitutive stimulation of HGF/MET signaling." (PMID 27121052, 2016). "It is widely accepted that hepatocyte growth factor (HGF) binding to receptor tyrosine kinase MET aggravates malignancy in a variety of cancers." (PMID 28018347, 2016). "Seed sequences for miRNA binding where also identified in signaling pathways and regulatory molecules such as Molecular Mechanisms of Cancer, HGF, NGF and ErbB, which promote the growth and survival of macrophages." (PMID 27119502, 2016). "(−)-Oleocanthal has been also tested for its ability to inhibit HGF/c-Met signaling in this cancer model." (PMID 27086914, 2016). "Several growth factors such as Nodal, Lefty, FGF, HB-EGF and HGF as well as transcription factors (e.g. Pitx2, FoxA2) are considered candidates with overlapping functions in cancer and development laterality." (PMID 27383829, 2016). "The percentages of high HGF expression in stromal fibroblasts and cancer cells were 46.3% (62/134) and 82.1% (110/134), respectively." (PMID 27374174, 2016). "We provide evidence that EGF- and HGF-induced phenotypic changes, ultimately leading to cancer-related death, are dependent on MCT1 expression, independent of MCT1 transporter activity." (PMID 27127175, 2016). "The MET kinase inhibitor, JNJ 38877605, completely prevented both HGF and fibroblast-induced migration of cancer cells." (PMID 27121052, 2016). "As the Met receptor is recognized to be one of the major therapeutic targets of the hallmarks of cancer, dietary phytochemicals acting as natural HGF/Met inhibitors are likely to have therapeutic value in preventing cancer invasion and metastasis." (PMID 27270323, 2016). "Previous reports demonstrated phosphorylation of β-catenin at Y142 in response to HGF in cancer cells and cultured hippocampal neurons." (PMID 27595133, 2016). "HGF, a mediator of cancer development and progression, is mainly secreted from fibroblasts, whereas its receptor, c-Met, is primarily expressed in epithelial cancer cells." (PMID 26828520, 2016). "The HGF-Met signaling has important biological roles in both normal development and cancer progression." (PMID 27608665, 2016). "Various clinical trials were conducted to evaluate the safety and efficacy of selective HGF/MET inhibitors in cancer patients." (PMID 27013592, 2016). "Meanwhile, MACC1 contributes to tumorigenesis through the promotion of cancer cell proliferation and invasion through activation of the HGF/ Met signaling pathway." (PMID 27832750, 2016). "In the range of noncytotoxic concentrations, vanillin also exhibits inhibitory effects on hepatocyte growth factor- (HGF-) induced migration of human lung A549 carcinoma cells, this due to inhibitory activity of phosphatidylinositol 3-kinase (PI3K)." (PMID 28077989, 2016). "The Rho GTPase can be activated downstream of the Met receptor, and inhibition of Rho or its effector Rho kinase (ROCK) decreases actin bundle formation and suppresses HGF-induced cancer cell spreading." (PMID 25946048, 2015). "It has been reported that activation of the HGF/c-Met pathway promotes cell invasion, migration and allows cancer metastasis." (PMID 25971889, 2015). "Both mAbs and small-molecule HGF/MET inhibitors have shown clinical benefits in patients with cancer, and they are different in terms of pharmacological properties and their underlying mechanisms of action." (PMID 28536405, 2015).
cancer (continued). "Pancreatic stellate cells enhance fibrosis, partly through HGF production, leading to sequestration of chemotherapeutic agents in the stromal compartment, impairing successful drug delivery to cancer cells." (PMID 26404380, 2015). "Furthermore, treatment with HGF was associated with lamellipodia formation, focal adhesion kinase phosphorylation and focal adhesion kinase expression at focal contacts, suggesting that c-Met and focal adhesion kinase cooperate to promote cancer cell/substrate adhesion." (PMID 25887320, 2015). "We also dissect the potential use of new molecules that interfere with the HGF/c-MET axis as therapeutic targets for future clinical trials in cancer disease." (PMID 28536400, 2015). "Elevated plasma levels of HGF have been suggested to correlate with a poor prognosis for several forms of cancer, including HCC." (PMID 28943627, 2015). "Studies have confirmed that the HGF/c-met system can activate proliferation, differentiation and adhesion of cancer cells, as well as increase cancer invasion and metastasis." (PMID 25658794, 2015). "Anti-HGF antibody (200 ng/ml) effectively suppressed c-Met, AKT, and ERK activation induced by recombinant HGF (50 ng/ml) in HCT116 cancer cells." (PMID 26090722, 2015). "HGF produced by stromal fibroblasts acts on cancer cells stimulating them not only to metastasize, but also to secrete HGF factor inducers by enhancing the connection between cancer cells and stroma mediated by HGF." (PMID 28536400, 2015). "c-Met, a high affinity receptor for HGF, plays a critical role in cancer growth, invasion and metastasis." (PMID 25886575, 2015). "In conclusion, treatment with the cMET inhibitor INC280 impairs both hypoxia-induced MDR-1 expression and HGF-mediated effects on growth, motility and signaling intermediates in gemcitabine resistant cancer cells in vitro." (PMID 25884642, 2015). "The HGF/c-Met pathway is activated in various types of cancer, which stimulates cancer cell growth and metastasis." (PMID 25971889, 2015). "The functions of HGF were further elucidated by in vitro and in vivo analyses using various types of cancer cell." (PMID 25592281, 2015). "Antagonists of the HGF/c-Met pathway represent potential anti-cancer agents to inhibit cancer infiltration and metastasis, and therefore, the development of such antagonists is currently underway." (PMID 25592281, 2015). "We dissect the potential use of new molecules that interfere with the HGF/c-MET axis as therapeutic targets for future clinical trials in cancer disease." (PMID 28536400, 2015). "Collective biochemical and genetic evidence suggests an association between dysregulated HGF/MET signaling and selected human cancers." (PMID 28536405, 2015). "Hepatocyte growth factor (HGF) confers EGFR TKI resistance by inducing two cancer-promoting functions." (PMID 26405162, 2015). "Hepatocyte growth factor (HGF) is a cytokine that has strong effects on normal cells and cancer cells." (PMID 26310485, 2015). "This has also been demonstrated in cancer-associated fibroblasts (CAF) isolated from HCC, where treatment of CAF-conditioned media with an anti-HGF antibody significantly reduced HCC proliferation in Hep3B and MHCC97L cell lines." (PMID 26013123, 2015). "HGF is a growth factor that exerts multiple effects; it promotes cell proliferation, migration and angiogenesis in cancer." (PMID 26099202, 2015). "The present study proposes the negative regulation mechanisms by methylation and SNP in intron 1 of HGF for HGF expression in cancer cells with short poly(dA)." (PMID 25436000, 2015). "Hepatocyte growth factor (HGF)is a cytokine that has a profound effect on cancer cells by stimulating migration and invasion and acting as an angiogenic factor." (PMID 26310485, 2015). "During hypoxia-induced angiogenesis, HGF facilitates cancer cell-endothelial cell contact through FAK (focal adhesion kinase) phosphorylation and decreases endothelial occludin, a primary protein in endothelial tight junctions." (PMID 26404380, 2015).
cancer (continued). "In cancer, EMT is thought to be induced by signals from the stroma associated with tumors, such as hepatocyte growth factor, platelet-derived growth factor, and transforming growth factor-beta." (PMID 25633122, 2015). "Among the metastatic factors, the scatter factor HGF was highlighted to be involved in the progression of cancer, including HCC." (PMID 25607934, 2015). "In the present study, the poly(dA) mononucleotide tract in various types of human cancer cell lines was examined and compared with the HGF expression levels in those cells." (PMID 25436000, 2015). "Much progress has been made in our understanding of c-Met/HGF signalling in recent years, and there is now convincing in vitro and in vivo evidence that this is an important pathway in mammary development and cancer progression." (PMID 25887320, 2015). "Growth factors, such as HGF or FGFs secreted by fibroblasts influence cell proliferation and resistance to lapatinib in some cancer cell lines, although the degree of dependence differs among the cell lines." (PMID 25884729, 2015). "c-Met is a RTK for the ligand hepatocyte growth factor (HGF), which is secreted by mesenchymal cells and cancer cells." (PMID 27280107, 2015). "For instance, circulating HGF was evaluated as a pharmacodynamic biomarker of MET inhibition by onartuzumab in patients with advanced cancers or with NSCLC." (PMID 28536405, 2015). "Based on these premises, the purpose of this study is to understand the role of fibroblasts-derived HGF in mediating the chemoresistance phenotype of cancer cells and the mechanism by which this occurs." (PMID 26090722, 2015). "The viability of cancer cells in the CM from fibroblasts was significantly decreased by the addition of 200 ng/ml of the anti-HGF antibody." (PMID 26090722, 2015). "Aberrant activation of the hepatocyte growth factor (HGF) receptor tyrosine kinase MET, mostly due to overexpression of the MET gene, is a common event in numerous types of human cancers and is frequently associated with poor prognosis." (PMID 26413215, 2015). "This work is currently ongoing, though the observed relationship between HGFl and PLCγ are of interest, given the role of PLCγ signaling in cell motility, cancer progression and invasion, and its links to HGF-induced cancer invasion and motility." (PMID 28536402, 2015). "Future studies are needed to identify cell types that rely on hyperactive Abl kinases to promote invasion and other morphogenetic processes in response to HGF/Met-dependent and—independent signaling during normal development and cancer." (PMID 25946048, 2015). "In this review, recent progress in HGF/MET pathway-targeted therapy for cancer treatment, the therapeutic potential of HGF/MET-targeted agents, and challenges in the development of such agents will be discussed." (PMID 28536405, 2015). "To examine the effects of anti-HGF antibody on cell signaling and apoptosis in cancer cells, we performed Western blot analysis." (PMID 26090722, 2015). "Several agents that have been tested in preclinical studies or clinical trials target the soluble mediators of the interactions between CAFs and cancer cells, including HGF, TGF-β, and CXCL12." (PMID 26473929, 2015). "Among the growth-factor-mediated cancer signaling, the HGF/c-Met axis is intimately related to the metastatic transformation of HCC." (PMID 25607934, 2015). "Neutralization of fibroblast-derived HGF maintained the reduction in cell viability induced by CPT-11 indicating that HGF targeting significantly enhances CPT-11 stimulated anti-cancer activity." (PMID 26090722, 2015). "A crosstalk mediated by HGF/c-Met between ASCs and cancer cells, stimulates acquisition of highly invasive capabilities of cancer cells, which increased their growth rate and self-renewal potential, supported by beta-catenin activation." (PMID 24327602, 2014).